MRPL12 (mitochondrial ribosomal protein L12)
Diseases named in the same sentence as MRPL12 in open-access papers (continued):
Sharing a sentence is not in itself a finding about the gene and the disease.
tumor (continued). "However, we unexpectedly observed that the difference in MRPL12 K163 acetylation between tumor and normal tissues (NTL) gradually decreased from stage I to stage IV." (PMID 40858596, 2025). "Conversely, the UBASH3B H391A mutant, an inactivated tyrosine phosphatase, failed to reverse the tumor malignant phenotype caused by MRPL12 overexpression (6K and S5I and 5 J)." (PMID 39343960, 2024). "Indeed, studies have shown that alterations in mitochondrial ribosomal protein L12 (MRPL12), essential for mitochondrial ribosome biogenesis, significantly reduce tumor cell growth in HCC cell lines and patient-derived organoids." (PMID 39451244, 2024). "In addition, the relationship between MRPL12 expression and the infiltration levels of 28 tumor-infiltrating lymphocytes (TILs) was evaluated via TISIDB." (PMID 36769082, 2023). "Additionally, the expression of MRPL12 in LUAD is significantly associated with immune regulatory factors, chemokines, and the infiltration levels of various immune cells, suggesting its potential role in the tumor immune microenvironment." (PMID 40371222, 2025). "In summary, MRPL12 acts as a novel oncogene in LUAD, promoting tumor development through mitochondrial metabolism reprogramming towards OXPHOS." (PMID 40371222, 2025). "YTHDC2 also targeted m6A-modified mitochondrial ribosomal protein L12 (MRPL12) mRNA, inhibiting LUAD tumor growth and metastasis, while promoting apoptosis, and ultimately suppressing tumor occurrence." (PMID 38790013, 2024). "MRPL12 is upregulated in LUAD and promotes tumor progression by enhancing mitochondrial OXPHOS." (PMID 40371222, 2025). "In contrast, no significant changes in tumor size and weight were observed in the MRPL12 Y60A overexpression group compared to the control group." (PMID 39343960, 2024). "We found that overexpression of UBASH3B inhibited the tumor phenotype induced by MRPL12 WT overexpression but did not affect the tumor phenotype induced by MRPL12 Y60E overexpression." (PMID 39343960, 2024). "Furthermore, changes in phosphorylation levels at MRPL12 Y60 in other tumors and the role of this modification in tumor development have not been reported." (PMID 39343960, 2024). "In addition, gross images, HE and IHC staining also revealed that lefamulin alone or in combination with sorafenib/regorafenib treatment could reduce tumor densities, and accompanied by a lower level of Ki67‐positive cells and MRPL12 expression, but did not affect ILF3 expression." (PMID 38874478, 2024). "Firstly, the expression level and biological function of MRPL12 in LUAD cells were validated, but the knockdown efficiency of sh-MRPL12 in LUAD cells was not confirmed by detecting protein expression, and the potential molecular mechanisms of MRPL12 in tumor progression were not examined." (PMID 36769082, 2023).
cancer (6 papers, 2020 to 2025). A tumor composed of atypical neoplastic, often pleomorphic cells that invade other tissues. "Despite this, the role and regulatory mechanisms underlying MRPL12’s transcriptional activity in cancers remain unexplored." (PMID 39343960, 2024). "MRPL12 exerts a pathogenic role in several diseases, including diabetic kidney disease and cancer." (PMID 36769082, 2023). "The negative correlation between MRPL12 and these immune cells further supports that MRPL12 overexpression restrains cancer immunity, thus contributing to cancer development and the poor survival of LUAD patients." (PMID 36769082, 2023). "We hypothesize that MRPL12 may also promote cancer progression in other tumors, especially those primarily driven by mitochondrial oxidative phosphorylation." (PMID 39343960, 2024). "MRPL12 was significantly correlated with the abundance of TILs across various cancer types." (PMID 36769082, 2023). "Thus, it is important to explore whether MRPL12 Y60 phosphorylation has similar effects in other cancers, as this could provide a theoretical basis for targeting this site in various tumors." (PMID 39343960, 2024). "MRPL12 mRNA expression was higher in LUAD tissues than in normal tissues and analyzed by gender, cancer stages, and nodal metastasis status." (PMID 36769082, 2023). "However, the necessity for MRPL12 in transcription is not seen in all studies, warranting further exploration of the function of MRPL12 in transcription, especially in light of the differential expression of MRPL12 observed in some cancers and neurological disorders." (PMID 33127643, 2020).
infection (1 paper, 2024). The state of being infected such as from the introduction of a foreign agent such as serum, vaccine, antigenic substance or organism. "Additionally, positive interactors of DCAF11 that were lost upon infection encompass splicing factors THRAP3 and SRSF5, the microtubule-associated protein MAP4, mitochondrial ribosomal protein MRPL12, and the TUFM mitochondrial translation elongation factor." (PMID 39383947, 2024).
kidney (1 paper, 2021). "After the role of ING2, along with its modulating mechanism on MRPL12 and mitochondrial OXPHOS, in ischemic induced TEC injury was established, we continued to determine whether ING2 could serve as one intervening target for ischemic kidney injuries." (PMID 34434929, 2021).
mitochondrial disease (1 paper, 2022). "Mitochondrial disease-causing mutations were found in thirteen small ribosomal subunit mitoribosomal proteins (MRPS1, MRPS2, MRPS6, MRPS7, MRPS9, MRPS11, MRPS14, MRPS16; MRPS22, MRPS23, MRPS25, MRPS34, MRPS39) and four large ribosomal mitochondrial proteins (MRPL3, MRPL12, MRPL24, MRPL44)." (PMID 36140315, 2022).
MRPL12 also shares sentences with these, for which no sentence is quoted: metabolic disease (2 papers); acute kidney injury (1); adenocarcinoma (1); hyperplasia (1); neurological disorders (1); pancreatic cancer (1); prostate carcinoma (1); renal carcinoma (1).